CFL1 (cofilin 1)
Diseases named in the same sentence as CFL1 in open-access papers (continued):
Sharing a sentence is not in itself a finding about the gene and the disease.
tumor (continued). "CFL1 is a small, ubiquitous, actin-binding protein that plays important roles in cytokinesis, endocytosis, apoptosis, cell proliferation, and migration, as well as in tumor development, infiltration, and metastasis." (PMID 35547358, 2022). "Taken together, our study revealed that miR-107 expression was downregulated in drug resistant HCC cell line and the upregulation of miR-107 induced cell death via ROS accumulation and inhibited tumor growth in part through regulating the expression of cofilin-1." (PMID 33901009, 2021). "To uncover tumor-promoting mechanisms of CFL1, we built a gene regulatory network." (PMID 33578795, 2021). "Moreover, univariate analysis showed that tumour size, tumour number, TNM stage, venous infiltration, HBV infection, and CFL1 level were significantly associated with HCC patients’ OS." (PMID 33784016, 2021). "Herein, we first found that CFL1 significantly correlated with the markers that were closely related to HCC tumor metastasis, showing that CFL1 may also play an important role on metastasis in HCC." (PMID 33791303, 2021). "Inhibition of CFL1 activity can reduce the movement and migration of tumor cells, which may be an important target for inhibiting tumor growth and proliferation." (PMID 33791303, 2021). "It is possible to speculate that the invasive margin may be region within the tumor that exhibits the highest levels of CFL-1, which increases aggressiveness and leads to local dissemination." (PMID 33482809, 2021). "We first compared the expression level of CFL1 between tumor tissues and paracancerous tissues." (PMID 33791303, 2021). "Over expression of cofilin-1 in astrocytoma cells enhanced the motility of tumor cells which could be as marker for malignancy." (PMID 33171868, 2020). "Also, xenograft tumor of miR-182-5p inhibitor and Cofilin 1 groups are more weight than control (p < 0.01)." (PMID 30858759, 2019). "Studies have shown that inhibiting CFL1 activity in a malignant tumor may be a potential target for the inhibition of tumor progression and metastasis." (PMID 29347944, 2018). "However, increased expression of CFL1 in tumours is not only related to the cytoplasmic region, but also to the cell nucleus." (PMID 29581975, 2018). "CFL1 may well become a new target for the treatment of malignant tumor cells undergoing the EMT, invasion and metastasis." (PMID 28388575, 2017). "In addition, Cofilin 1 binds to F-actin and induces remodeling of the actin cytoskeleton, resulting in increased tumor cell motility, invasion, and metastasis." (PMID 29190896, 2017). "CFL1 expression was markedly greater in tumor tissues than in control normal stomach tissues." (PMID 28388575, 2017). "In view of the anti-metastatic effect of Rh2E2 in vivo, proteomic profiling provided evidence that several tumor metastatic markers, such as α-enolase, stathmin, cofilin-1, Rho GDP-dissociation inhibitor 1 and thromboxane-A synthase, probably participate in the anti-metastatic actions of Rh2E2." (PMID 26799418, 2016). "Indeed, cofilin-1 signaling plays a pivotal role in the regulation of efficient EGFR vesicular trafficking in invasive tumor cell." (PMID 25784483, 2015). "Furthermore, our data demonstrate that NAV2 promotes CRC invasion and metastasis by regulating F-actin polymerization via the SSH1L/cofilin-1 pathway and boosting tumor budding generation in terms of pathologic morphology." (PMID 26452645, 2015). "By immunohistochemical analysis, total cofilin-1 and p-cofilin apparently also showed higher expression in tumor than in normal epithelium and, although the differences were not large, the results agreed with those obtained by our proteomic experiments and by other authors." (PMID 23227181, 2012). "The tumor nodules were significantly reduced in cofilin-1-ShRNA -treated mice." (PMID 22087286, 2011). "In addition, the shRNA expressing plasmid targeting cofilin-1 significantly inhibited tumor metastases and prolonged survival in LL/2 metastatic model." (PMID 22087286, 2011).
tumor (continued). "Our results showed that cofilin-1-ShRNA delayed tumor metastasis and prolonged mice survival obviously, which suggested that cofilin-1 might serve as a potential target for lung metastases therapy." (PMID 22087286, 2011). "Furthermore, CFL1 is expressed more highly in portal vein tumor thrombus (pvtt) than in HCC tumor tissues, and an increase in CFL1 expression is closely related to adverse clinical features, making it an independent risk predictor for the overall survival of HCC patients." (PMID 40051627, 2025). "Moreover, much higher CFL1 expression could be observed in the tumor tissues of HCC patients with relapse within postoperative 1 year." (PMID 37203277, 2023). "Additionally, Cofilin-1 is essential for the maturation of EVs and may also play a key role in the establishment of the pre-metastatic niche, thus promoting tumour cell migration." (PMID 34678587, 2022). "Our IHC profiling identified a direct association between CFL-1 and SSH1 levels with lymph node metastasis in CRC tissues, which was significantly correlated with lymph node metastasis risk by univariate analysis, supporting their role in local tumor dissemination." (PMID 33482809, 2021). "Therefore, Cofilin 1 may become a new potential tumor marker and target for treatment of malignant tumor." (PMID 30858759, 2019). "Therefore, CFL1 plays an important role in several aspects in tumor cells, including determining the migration speed, invasiveness, direction of motion, and nuclear division, and also affects the adhesion of the tumor cells and matrix." (PMID 29347944, 2018). "Thus, CFL1 not only serves as one of the key factors that promotes the cell transition from a stationary state to a moving state but also plays an important role in the movement of tumor cells." (PMID 29347944, 2018). "Thus, both PGK1 and CFL1 have some effects on tumor invasion, proliferation and metastasis, but whether they are associated with tumor cell radiosensibility remains unknown." (PMID 28903403, 2017). "Dysregulation of CFL1 may impact tumor proliferation and invasion." (PMID 28903403, 2017). "Upregulation of Cofilin-1 (CFL1), a tumor progression marker deemed a “metastasis switch”, is one of the mechanisms by which tumor cells develop radiation resistance." (PMID 38675144, 2024). "Cofilin 1 (CFL1) is a crucial regulator of actin dynamics and cell migration, and is generally regarded as an accessory in tumor cell invasion and movement." (PMID 38684875, 2024). "Based on this regulatory mechanism, systemic co‐delivery of siCFL1 and sorafenib with reduction‐responsive nanoparticles can effectively silence CFL1 expression and significantly inhibit HCC patient‐derived xenografts tumor growth." (PMID 37203277, 2023). "Similar as the results of MHCC‐97L xenograft tumors, histological analysis also demonstrates that the NPs(siCFL1/Sor) are the most effective in suppressing CFL1 expression and inhibiting the PDX tumor growth." (PMID 37203277, 2023). "Recently, there have also been a number of studies suggesting that CFL1 and CAP1 work in conjunction to influence the aggressiveness of tumor development." (PMID 37226274, 2022). "When tumor samples were separate into high or low SSH1 expression groups, the SSH1 IHC score was significantly related to lymph node metastasis, similar to CFL-1 data." (PMID 33482809, 2021). "Real‐time quantitative PCR, immunostaining, and immunoblotting were performed to detect cofilin 1 (CFL1) in HCC and non‐tumour tissues." (PMID 33784016, 2021). "CFL-1, LIMK1 and SSH1 mRNA/protein levels were assessed by real-time PCR and immunohistochemical analyses using normal adjacent and tumor tissues obtained from a clinical cohort of CRC patients." (PMID 33482809, 2021). "Regarding the clinical and biological significance of CFL-1 and SSH1 in CRC, we found that CFL-1 and SSH1 mRNA levels were downregulated in all tumor stages when analyzed by bioinformatic." (PMID 33482809, 2021).
tumor (continued). "To confirm the results obtained by bioinformatic analysis, we evaluated CFL-1, LIMK1, and SSH1 mRNA levels by RT-qPCR using tumor tissues from patients with CRC paired with adjacent normal tissues in a clinical cohort." (PMID 33482809, 2021). "Increased expression of CFL1 was observed in HCC patients infected with HBV (p = 0.016), tumour diameter ≥5 cm (p = 0.013), multiple tumours (p = 0.033), vascular invasion (p < 0.001), and advanced Tumor‐Nodes‐Metastasis stage (p = 0.002)." (PMID 33784016, 2021). "The results showed that the number of tumor (P = 0.040), portal vein tumor thrombus (PVTT) (P = 0.005), and microvascular invasion (MVI) (P = 0.009) were closely related with CFL1 expression." (PMID 33791303, 2021). "Heterogeneous expression for CFL-1, SSH1 and LIMK1 were detected when tumor tissues were paired with adjacent normal samples." (PMID 33482809, 2021). "Here, we also disclosed that CFL1 promoted not only migration, proliferation and invasion, but also EMT in HCC cells and its knockdown repressed tumour extensiveness and metastasis in vivo." (PMID 33784016, 2021). "In accordance with these data, studies using bladder, prostate, and gastric models have also correlated CFL-1 and LIMK1 expression pathways with the EMT program, as well as tumor initiation and metastatic colonization in breast model." (PMID 33482809, 2021). "LIMK1 expression was upregulated (P < 0.0001) whereas CFL-1 and SSH1 were downregulated (P < 0.0001) in all tumor stages when compared with normal tissues." (PMID 33482809, 2021). "miR-182-5p mimics, miR-182-5p inhibitor and Cofilin 1 expression vectors transfected RT4 cells were injected into nude mice, then, tumor volume was determined every few days." (PMID 30858759, 2019). "GAS6, AXL, and Cofilin-1 are overexpressed, but because of tissue-specific functions of claudins family, Claudin-1 may have a different role in various cancers; depending on the origin of cancer cells and the adjacent tumor microenvironment, it may increase or decrease in various cancers." (PMID 31700829, 2019). "KU treatment downregulated the epithelial-mesenchymal markers Twist, Snail, and Slug and the metastasis-related genes CAPN1, CDC42, CFL1, IGF1, WASF1, and WASL in cells and tumor tissues." (PMID 30390003, 2018). "Cofilin-1 (CFL1), a small protein of 18 kDa, has been studied as a biomarker dueto its involvement in tumor cell migration and invasion." (PMID 29846436, 2018). "While 10 ng/mL TGF-β1 successfully induced tumor cell EMT, silencing of CFL1 significantly inhibited cell invasion and metastasis." (PMID 28388575, 2017). "Therefore, we speculate that CFL1 may promote tumor development." (PMID 28388575, 2017). "Tumor volumes were lower in mice injected with Cofilin 1 knockdown T24 and RT4 cells (si-Cofilin 1) than that in the control group (NC group)." (PMID 29190896, 2017). "Furthermore, the tumor suppressing function of miR-107 has been previously reported in HCC via targeting oncogenic genes, including RGS4, HMGA2, HMGCS2, cofilin-1, and Wnt/β-catenin." (PMID 37744274, 2023). "Having demonstrated the efficient CFL1 silencing by NPs(siCFL1/Sor) to enhance sorafenib sensitivity in vitro, we next evaluated whether these NPs could use this ability to inhibit HCC tumor growth." (PMID 37203277, 2023). "Systemic co‐delivery of sorafenib and siCFL1 by reduction‐responsive NPs could effectively silence CFL1 expression and enhance sorafenib sensitivity in vivo, thereby leading to a significant inhibition of HCC tumor growth." (PMID 37203277, 2023). "And in the hypoxic tumor microenvironment of HCC, CFL1 can be transcriptionally activated by hypoxia-inducible factor-1α (HIF-1α), and subsequently interacts with PLD1 to inhibit PLD1 ubiquitination degradation and stabilize its expression, thereby activating the AKT pathway." (PMID 36463115, 2022).
tumor (continued). "However, further investigation is required to determine the relationship between CFL-1 and SSH1 expression levels and their role in different areas of the tumor." (PMID 33482809, 2021). "Furthermore, IHC staining of CFL1, EMT markers (E‐cadherin, N‐cadherin, and Vimentin) was performed in subcutaneous tumour tissues and lung metastases." (PMID 33784016, 2021). "In contrast, CFL-1 and SSH1 have expression downregulated in all tumor stages." (PMID 33482809, 2021). "The precise balance between expression and subcellular localization of CFL-1, LIMK1, and SSH1 is pivotal for small changes in the dynamics of the actin cytoskeleton, and may augment features of tumor aggressiveness, including tumor dissemination." (PMID 33482809, 2021). "Cofilin 1 (CFL1) is a cytoskeletal reorganizer and EMT regulator in tumor cells." (PMID 32467737, 2020). "In this study, the expression levels of GAS6, AXL, Cofilin-1, Claudin-1, as genes involved in EMT, and their relationship with clinicopathological features include; age at diagnosis, TNM staging, size and grade of tumor were investigated in EOC patients." (PMID 31700829, 2019). "The decrease or increase in CFL1 pathway activity is mediated by LIM kinase-1 and results in the reduction and enhancement of metastasis, mobility, and vascular invasion of the corresponding tumor cells." (PMID 29347944, 2018). "Dstn like Cfl-1 promotes tumor cell migration and invasiveness, but in general the activities of Dstn and Cfl-1 are non-overlapping." (PMID 28025492, 2016). "In vivo studies also showed that the lung weight from PKM2 or cofilin-1-ShRNA treated group (normal mice, i.e. not bearing tumor) did not have significant changes compared with control groups (P>0.05)." (PMID 22087286, 2011). "Since CFL1 shows the strong ability to regulate sorafenib sensitivity, using NPs for systemic co‐delivery of sorafenib and siCFL1 could concurrently improve the accumulation of sorafenib in the HCC tumor tissues and enhance sorafenib sensitivity of HCC cells via silencing CFL1 expression." (PMID 37203277, 2023). "Based on the analysis of the number of subpopulations expressing CFL1, PFN1 and CAP1, the characteristics of CTCs pools and peripheral blood leukocyte pools in patients with HNSCC were given in relation to the main clinical and pathological characteristics of the tumor." (PMID 37226274, 2022). "Therefore, an analysis of the profile of gene and protein expression of CFL-1 and its regulators, LIMK1/SSH1, may provide important insights into the local invasion processes of primary tumor cells and could help in disease stratification in routine pathology." (PMID 33482809, 2021). "Exosomal Ribosomal Protein S3 (RPS3) secreted by cisplatin-resistant tumor cells could be taken up by cisplatin-sensitive cells and thus become chemo resistant (through activation of the PI3K-Akt-cofilin-1 signaling pathway), indicating its potential value for proper chemotherapeutics selection." (PMID 34307129, 2021). "Negative correlations across those tumor types were observed in four target genes (ARPC2, CFL1, PLIN3, RAP1GDS1)." (PMID 39201394, 2024). "Recently, nanoparticles-mediated co-delivery of cofilin 1 (CFL1) silencing with sorafenib, a chemotherapeutic agent, showed elevated inhibitory properties for HCC tumor growth without exhibiting significant toxicity." (PMID 39484162, 2024).
cancer (73 papers, 2011 to 2026). A tumor composed of atypical neoplastic, often pleomorphic cells that invade other tissues. "On the other hand, in cancer cells with high CFL1/actin ratio, CFL1 binds rapidly to F-actin, causing its saturation and stabilization into twisted form that allow its separation as CFL1-saturated actin bundles from the pointed ends." (PMID 37464436, 2023). "Although an association of CFL1 overexpression with cancer progression has previously been established, the molecular interactions regulating its behavior in cancer are far from understood." (PMID 33578795, 2021). "Cofilin 1 is located at 11q13, a chromosome region that is associated with invasion, metastasis, and decreased survival in cancer patients." (PMID 29190896, 2017). "The increased level of Cfl-1 in HMCs is often associated with poor prognosis which can be related with cofilin-dependent drug resistance of cancer cells." (PMID 28025492, 2016). "Additionally, it also helps cancer cells survival by preventing apoptosis, as higher level of cofilin-1 have been linked to resistance against chemotherapy and radiation therapy, both of which rely on apoptosis to kill cancer cells." (PMID 40297849, 2025). "In line with this, increased expression of CFL1 could be associated with proliferation, migration, or invasion in various types of cancer as well as with a poorer overall survival." (PMID 33578795, 2021). "The AUC was 0.70 and, at acut-off point ≥662.63 pg/mL, we obtained 60% sensitivity and 54% specificity.Logistic regression analysis controlled for tobacco history, histologic types,and N stage showed that cancer cell-associated CFL1 was an independent predictorof death." (PMID 29846436, 2018). "The metastasis of cancer is associated with the expression of proteins such as α-enolase, stathmin, cofilin-1, Rho GDP-dissociation inhibitor 1 and thromboxane-A synthase, which serve as potential prognostic markers and may participate in the anti-metastatic actions of 20(S/R)-Rh2E2." (PMID 32796841, 2020). "The level of phosphorylated cofilin (p-cofilin) was significantly decreased in cancer cells treated with M1 RBCs, while the total Cofilin-1 protein level remained unchanged, resulting in a significantly decreased p-cofilin/cofilin-1 ratio." (PMID 40301999, 2025). "Cofilin-1 regulates actin filament turnover and is required for cancer cell migration via cytoskeletal remodeling." (PMID 40723199, 2025). "Key genes (ACTIN1, LIMK1, CORO1C, INF2, SH3D21, CFL1, FSCN1, MYO1B) implicated in actin cytoskeleton organization were identified, suggesting their role in oral potentially malignant disorders and cancer progression." (PMID 40818124, 2025). "Research points to slingshot protein phosphatase 1 (SSH1), a modulator of cofilin-1 (CFL-1), as instrumental in the reformation of the actin cytoskeleton, thereby impacting the invasiveness of various cancer types." (PMID 37837551, 2023). "As the exact role of EVs in cancer progression emerges, in particular their complex role concerning cofilin-1 and actin, so too does the potential to target cofilin-1 for the treatment of metastatic TNBC." (PMID 34678587, 2022). "Recent studies have emerged regarding the potential role of cofilin-1 in promoting cancer growth and metastasis." (PMID 34678587, 2022). "The role of CFL1 in actin remodeling and thus migration and tissue invasion of cancer cells is well described." (PMID 33578795, 2021). "Otherwise, the inhibitory effects of CFL1 knockdown on cancer cell growth and metastasis in HCC were also confirmed in MHCC97H cells." (PMID 33784016, 2021). "These molecular mechanisms indicated that cofilin-1 which is very important gene to regulate cancer cells metastasis." (PMID 33901009, 2021). "One example is the actin-binding protein cofilin (CFL1) that regulates cancer cell motility and invasiveness." (PMID 33706810, 2021).